LINC00973 (long independently transcribed non-coding RNA 973)
Synonyms: L3EMP; CTD-2021J15.2
Gene: Long non-coding RNA gene on chromosome 3 (98,901,046 to 99,316,259, forward strand). Ensembl gene ENSG00000240476.
Diseases named in the same sentence as LINC00973 in open-access papers:
LINC00973 is named in the same sentence as 8 diseases in open-access papers, as found by Europe PMC text mining. Sharing a sentence is not in itself a finding about the gene and the disease. The quoted sentences say what the papers report.
colon cancer (3 papers, 2018 to 2025). "Besides, analysis of LINC00973 expression in colonic tumors and in cancer cell lines established from breast tumors at various stages of cancer progression demonstrated that LINC00973 over-expression predominantly occurs at late stages of tumor development." (PMID 33171937, 2020). "Further clinical studies are necessary in order to determine, if measurement of the LINC00973 abundance throughout the course of neoadjuvant therapy might be useful for the reliable prediction of colon cancer relapse." (PMID 30405205, 2018). "Besides, LINC00973 KO cells were much less resistant to chemotherapeutic drugs, which imply that overexpression of this RNA is a key event in the acquisition of chemoresistance by colon cancer cells." (PMID 30405205, 2018). "In the current work, we have compared the phenotypes of HT-29 colon cancer cells with CRISPR-mediated LINC00973 knockdown (LINC00973 KD) and cells with ectopic LINC00973 over-expression (LV2)." (PMID 33171937, 2020).
breast carcinoma (1 paper, 2025). "LINC00973 is also up-regulated in breast cancer and promotes tumor growth by regulating MAPK signaling." (PMID 41303378, 2025).
lung carcinoma (1 paper, 2021). "As we all know, gefitinib and erlotinib were common anti-cancer drugs for lung cancer, and Gefitinib and erlotinib could reduce the expression of carcinogenic LINC00973, which was expected to improve the prognosis of lung cancer patients." (PMID 34394080, 2021).
pancreatic cancer (1 paper, 2022). "In pancreatic cancer cells and tissues, qRT-PCR indicated the relative expression of LINC01091, LINC01133, TRPC7-AS1, and LINC00973." (PMID 36371178, 2022).
cancer (5 papers, 2018 to 2022). A tumor composed of atypical neoplastic, often pleomorphic cells that invade other tissues. "There were few studies on LINC00973 in cancer, but we first formally formalize the expression of LINC00973 in NSCLC tissues, and explore the ceRNA network regulation mechanism of LINC00973 to provide new candidate markers for the treatment of NSCLC." (PMID 34394080, 2021). "Obtained results demonstrated that LINC00973 is predominantly a nuclear RNA, which inhibits proliferation of normal and cancer cells by blocking S/G2 transition, inducing apoptosis in response to anti-cancer drugs." (PMID 33171937, 2020). "LINC00973 is involved in cancer immunosuppression via positive modulation of Siglec-15 in ccRCC." (PMID 36060659, 2022). "For example, chemotherapy could upregulate the expression level of LINC00973 in normal cells and cancer cells, which might be related to the activation of DNA damage response pathways or mitotic arrest." (PMID 34394080, 2021). "We found that anti-cancer drugs could inhibit the expression of LINC00973 in NSCLC PC9 and HCC827 cells." (PMID 34394080, 2021). "Additionally, LINC00973 was involved in cancer immunosuppression by modulating SIGLEC-15 in ccRCC." (PMID 36371178, 2022). "Indeed, according to the UCSC ChIP-Seq database, the LINC00973 promoter and its three enhancers contain nearly a dozen strong RUNX3 binding sites, which were detected in several cell cancer lines." (PMID 33171937, 2020).
tumor (5 papers, 2018 to 2026). "Mechanistically, LINC00973 functioned as a molecular sponge for tumor-suppressive miR-6756-3p, consequently stabilizing transcription factor Engrailed-2 (EN2) mRNA and activating NOTCH pathway to promote HNSCC progression." (PMID 41419462, 2025). "LINC00973 promoted cell proliferation, migration, and invasion and inhibited cell apoptosis and senescence in vitro, and induced tumor growth and lymph node metastasis in vivo." (PMID 41419462, 2025). "In this study, high-throughput sequencing analysis of paired NSCLC tumor tissues and adjacent non-tumorous samples revealed that LINC00973 is significantly upregulated in tumor specimens." (PMID 41684454, 2026).
LINC00973 also shares sentences with these, for which no sentence is quoted: breast tumors (1 paper); non-small cell lung carcinoma (1).